CAV2 (caveolin 2)
Diseases named in the same sentence as CAV2 in open-access papers (continued):
Sharing a sentence is not in itself a finding about the gene and the disease.
invasive breast carcinoma (1 paper, 2008). A carcinoma that infiltrates the breast parenchyma. "In this study, CAV1 expression was significantly associated with a shorter BCSS in patients with low grade invasive breast cancers whereas patients with CAV2-positive cancers had a shorter DFS." (PMID 18612310, 2008). "Caveolin-1 positivity was detected in 13.4% whereas CAV2 was found in 5.9% of invasive breast cancer cases." (PMID 18612310, 2008). "Despite the controversy about the distribution of CAV1 and CAV2 in normal and invasive breast cancer, recent studies confirmed the preferential expression of both genes and their proteins in normal myoepithelial cells." (PMID 18612310, 2008). "Caveolin-1 and CAV2 protein expression was assessed on a tissue microarray containing 880 unselected invasive breast cancer cases, by means of immunohistochemistry." (PMID 18612310, 2008).
invasive carcinoma (1 paper, 2025). A carcinoma that is not confined to the epithelium, and has spread to the surrounding stroma. "Pathological assessments at 23 weeks showed invasive carcinoma in 9 out of 10 wild-type mice, contrasting with its presence in just 1 out of 10 Cav2-/- counterparts." (PMID 41330921, 2025).
meningioma (1 paper, 2018). A generally slow growing tumor attached to the dura mater. "RUNDC3B, SCG2, SLC1A3, EXT1 (as well as RHOBTB3, TSPAN7, CAV2, MLPH) were part of the NF2/SMARCB1 expression subclass of a recent study on genomic profiling of meningioma." (PMID 29662628, 2018). "Six of these genes were usually underexpressed (RUNDC3B, ANGPT2, PHLDA2, CAV2, EDNRA, and SCG2) in non-aggressive/non-recurrent tumors and overexpressed in more aggressive/recurrent meningiomas." (PMID 29662628, 2018).
myocardial infarction (1 paper, 2011). Gross necrosis of the myocardium, as a result of interruption of the blood supply to the area, as in coronary thrombosis. "Interestingly, in the MCT and myocardial infarction models of PH, in addition to loss of caveolin-1, caveolin-2 loss occurs, and the rescue of caveolin-1 attenuates PH and also restores caveolin-2 expression." (PMID 21660237, 2011).
oral carcinomas (1 paper, 2025). "Summarizing, our findings suggest oral carcinomas can influence neural Cav2 levels in both nerve fibers and somas." (PMID 41330921, 2025). "We next probed whether the TG, which houses the neuronal somas for nerves that innervate the tongue, manifests Cav2 expression, and if such expression is perturbed by oral cancer in vivo." (PMID 41330921, 2025).
ovarian tumors (1 paper, 2023). "According to the HPA, high expression of CAV2, COL11A1, DNAJB4, THY1 and VCAN decreased the 5-year survival for breast, CNS, colon, kidney, lung and ovarian tumors." (PMID 37986165, 2023).
pancreatic ductal adenocarcinoma (1 paper, 2022). An infiltrating adenocarcinoma that arises from the epithelial cells of the pancreas. "In a study aiming to identify the functional genes and genetic variants associated with the prognosis of pancreatic ductal adenocarcinoma in 1070 patients, CAV2 was found to be upregulated and inversely associated with prognosis." (PMID 36114176, 2022).
papillary adenocarcinoma (1 paper, 2008). A morphologic variant of adenocarcinoma. "Significantly (P < 0.05) higher levels of Cav-1 and Cav-2 expression were detected in the carcinoma tumors compared to their papillary adenocarcinoma counterparts (2.8- and 3.8-fold, respectively)." (PMID 18811984, 2008).
pneumonitis (1 paper, 2004). An inflammatory process affecting the lung parenchyma. "Thus mouse pneumonitis strain, MoPn and LGV (L2) do not acquire caveolin-2, but they do express IncG." (PMID 15271223, 2004).
pulmonary diseases (1 paper, 2012). "In addition to caveolin-1, possible importance of the less-studied endothelial caveolin-2 in pulmonary diseases will be also discussed." (PMID 26605130, 2012). "In addition to overwhelming evidence for the role of endothelial caveolin-1, more recent studies also suggest that endothelial caveolin-2 could possibly play a role in pulmonary disease." (PMID 26605130, 2012).
pulmonary hypertension (1 paper, 2012). Increased pressure within the pulmonary circulation due to lung or heart disorder. "Further studies testing the possibility of pulmonary hypertension in Cav-2 KO mice will be necessary." (PMID 26605130, 2012). "Moreover, in addition to Cav-1, Cav-2 was also reduced in rats with moncrotaline-induced pulmonary hypertension." (PMID 26605130, 2012). "However, unlike in Cav-1 KO mice, the possibility that Cav-2 KO mice have pulmonary hypertension was not examined." (PMID 26605130, 2012).
Salmonella Infections (1 paper, 2013). Infections with bacteria of the genus SALMONELLA. "In particular, we became interested in the potential regulation of a major FA factor Caveolin 2 (CAV2) by miR-29a during Salmonella infection." (PMID 23826261, 2013). "To corroborate our hypothesis that miR-29a regulates the expression of CAV2, we performed RT-qPCRs detecting the ileal expression of CAV2 upon Salmonella infection." (PMID 23826261, 2013). "Our integrated analysis of miRNA and mRNA expression in intestinal Salmonella infection pointed out that FA members such as VCL and CAV2 but also ECM proteins that are involved in FA formation are controlled by miRNAs, particularly by miR-29a." (PMID 23826261, 2013). "Our data do not support the mentioned hypothesis since intestinal Salmonella infection led to significantly anti-correlated expression of miR-29a and CAV2 on transcriptional as well as translational level, while an obvious linkage to CDC42 was neither detected in vivo nor in vitro." (PMID 23826261, 2013).
schwannoma (1 paper, 2025). A benign, usually encapsulated slow growing tumor composed of Schwann cells. "Two blue module genes that are essential to ECM, CAV1 and CAV2, were conserved in both hiPSC and mouse derived SCs and may be linked to NF2-associated vesicle trafficking as previously shown in schwannoma." (PMID 40585242, 2025).
tongue tumors (1 paper, 2025). "Notably, the knockout of Cav2, either globally or specifically in sensory neurons or glial cells, markedly attenuates the growth of orthotopically implanted tongue tumors." (PMID 41330921, 2025).
tumor (55 papers, 2004 to 2026). "Our findings highlight that cancer cells drive an increase in caveolin-2 (Cav2) expression within trigeminal ganglia and associated neural fibers in the tumor milieu, fostering a reciprocal attractant relationship between tumor cells and nerves." (PMID 41330921, 2025). "In order to effectively assess the expression of Cav2 in tumor-associated neoneurogenesis, we conducted an additional set of experiments." (PMID 41330921, 2025). "Strikingly, phosphorylation of S6 was significantly higher in wild-type mice compared to Cav2-deficient mice, and this elevation was particularly prominent at the invasive tumor margin." (PMID 41330921, 2025). "We found that the tumor invasion towards the nerve index (α/β) markedly decreased upon substituting wild-type TGs with Cav2 knockout variants." (PMID 41330921, 2025). "The high expression of CAV2 has been associated with the progression of several types of tumours, including those of the lung, prostate, kidney, and breast." (PMID 35517414, 2022). "In a Cav-2 KO mouse model, its loss seems to favor infiltration of tumor-associated macrophages into the tumor tissue and tumor regression." (PMID 33195223, 2020). "Future studies will be required to establish the more exact mechanisms via which loss of Cav-2 in the host leads to tumor regression." (PMID 31831780, 2019). "As we originally found an association of CAV2 expression in the tumor tissue, we also combined the results from tumor and stromal expression." (PMID 29850392, 2018). "Noteworthy events include upregulation of apoptosis (Bcl)-related gene Bid3 and downregulation of Cav2 tumor suppressor and metastasis-linked Nupr1." (PMID 22260314, 2012). "CAV2 expression was associated with high tumour grade (P=0.005), large tumour size (P<0.001) and poor Nottingham prognostic index (P=0.017)." (PMID 18612310, 2008). "Additionally, quantitative analysis of β3-tubulin staining was performed to determine the impact of Cav2 loss on nerve density within the tumor microenvironment." (PMID 41330921, 2025). "A significant suppression of tumor growth in Cav2-deficient mice was recorded for both HNSCC lines." (PMID 41330921, 2025). "In fact, CAV2 is a gene encoding caveolin 2, which is involved in basic cell functions, including signal transduction, lipid metabolism, control of cell growth, and apoptosis; it may have tumor suppressor effects." (PMID 35178391, 2022). "Only few data are found regarding the association of stromal CAV2 with tumor progression." (PMID 29850392, 2018). "The expression of caveolin-1 (CAV1) in both tumor cell and cancer-associated fibroblasts (CAFs) has been found to correlate with tumor aggressiveness in different epithelial tumor entities, whereas less is known for caveolin-2 (CAV2)." (PMID 29850392, 2018). "Notably, CAV2 deficiency synergized with Cetuximab treatment, reducing the the half maximal inhibitory concentration (IC50) value by 6-fold compared with control cells and suppressing tumor growth by 48.41% in xenograft models compared to Cetuximab monotherapy (p < 0.0001)." (PMID 41976369, 2026). "Next, we evaluated the potential influence of neural Cav2 on nerve-directed tumor cell infiltration." (PMID 41330921, 2025). "As expected, the presence of wild-type TGs significantly bolstered tumor formation, a phenomenon abrogated in Cav2-/- TGs." (PMID 41330921, 2025). "This was highlighted by a dramatic decrease in MOC2 and MOC1 tumor volume in Cav2-/- mice by nearly 17-fold and 23-fold, respectively, compared to their wild-type counterparts." (PMID 41330921, 2025). "This overexpression of Cav2 in nerves, in turn, fosters stemness characteristics in tumor cells, primarily by inducing a metabolic shift towards mitochondrial OXPHOS." (PMID 41330921, 2025). "In contrast, CAV2 expression was markedly elevated in PNI positive cases, and CAV2 predominantly localized to nerve structures within the tumor microenvironment." (PMID 41330921, 2025).
tumor (continued). "Collectively, these findings suggest that Cav2+/+ nerves are facilitators of tumor cell stemness, likely through an enhancement of oxidative phosphorylation." (PMID 41330921, 2025). "Histological evaluations of HNSCC samples revealed a pronounced enrichment of CAV2 within neural structures, relative to other components in the tumor microenvironment." (PMID 41330921, 2025). "Upon orthotopic implantation of MOC2 cells, AdvCreCav2f/f mice displayed a significant reduction in tumor volume compared to their Cav2f/f counterparts, confirming the contributory role of neuronal Cav2 in tumor development." (PMID 41330921, 2025). "Subsequent histological evaluations of human HNSCC specimens revealed a tendency for an increased presence of CD44+ cancer cells in tumor zones in close proximity to neural niches with high CAV2 expression." (PMID 41330921, 2025). "To elucidate the mechanism by which neural Cav2 influences tumor cell phenotype, we first analyzed the subcellular localization of Cav2 in neural cells." (PMID 41330921, 2025). "Following co-culture with tumor cells, Cav2 was found to localize to the axons and axonal surface in a subset of cells." (PMID 41330921, 2025). "Comparative analysis revealed that axonal length and neural filament quantity in Cav2+/+ neurons co-cultured with tumor cells notably exceeded those in Cav2-/- counterparts." (PMID 41330921, 2025). "A rise in the Cav2+ nerve fraction relative to sensory nerve counts was also evident through tumor progression." (PMID 41330921, 2025). "The results showed that tumor cells co-cultured with Cav2-/- TG exhibited relatively higher lactate secretion." (PMID 41330921, 2025). "First, after enzymatic digestion of Cav2+/+ and Cav2-/- TGs, we used cytosine arabinoside to inhibit glial cell growth, thereby enriching for neurons, which were subsequently co-cultured with tumor cells." (PMID 41330921, 2025). "To evaluate the in vivo effects of Cav2+/+ nerves on tumor cell behavior, we employed an orthotopically co-injection model." (PMID 41330921, 2025). "Our findings indicate that cancer cells trigger an upregulation of Cav2 in both neuronal cell bodies within ganglia and nerve fibers within the tumor microenvironment." (PMID 41330921, 2025). "To comprehensively elucidate Cav2’s role throughout the tumor development trajectory, we initiated a separate set of experiments." (PMID 41330921, 2025). "Seeking insights into the mechanisms by which neural Cav2 influences mitochondrial oxidative phosphorylation (OXPHOS) in cancer cells, we explored the effect of Cav2+/+ TGs on tumor cell mitochondrial biogenesis." (PMID 41330921, 2025). "We demonstrate that the genetic ablation of Cav2 in both neuronal and glial cells significantly impedes tumorigenesis and decreases tumor incidence." (PMID 41330921, 2025). "Results indicated that mitochondrial superoxide level in tumor cells co-cultured with Cav2-/- TG neurons was relatively lower compared to the control group (p = 0.057)." (PMID 41330921, 2025). "Our study confirms that neurogenic Cav2 is a critical molecular pathway through which the tumor microenvironment influences tumor stemness, offering potential targets and strategies for cancer treatment." (PMID 41330921, 2025). "CAV2-AU-M2 showed selective replication in the OS cells and induced efficient tumor cell lysis and death." (PMID 38391964, 2024). "Data in the HPA database suggested that CAV2 was highly expressed in the tumor, consistent with the transcriptional level, while the other genes were not expressed consistent with the transcriptional level." (PMID 36950136, 2023). "It has previously been shown in caveolin (Cav)-1, Cav-2, and Cav-3; additionally, in Cav-1 and Cav-2, major structural proteins of caveolae infectious tumor metastasis." (PMID 37511762, 2023). "Analysis and group comparison indicated that the mRNA expression levels of CAV1 and CAV2 genes were significantly higher in tumor tissues compared with those in normal tissues." (PMID 36830672, 2023).
tumor (continued). "The expression of several race-associated genes was also dependent on the MED12 mutation status of the tumor, being higher (FRAT2, TNFRSF19, ACP7, IRS4, PLEKHG4B, KRT17, SLN, and ZNF703) or lower (CAV2) in the mutated specimens compared with wild-type tumors." (PMID 37686244, 2023). "The top three downregulated genes in tumor-bearing group of female mice were Ctgf (cellular communication network factor 2, FC = 0.276, p = 0.0007), Cav2 (caveolin 2, FC = 0.305, p < 0.0014) and Tek (TEK receptor tyrosine kinase, FC = 0.32, p < 0.0021)." (PMID 37573456, 2023). "We performed data analysis between the expression levels of CAV1 and CAV2 with the location of the primary tumor and patients’ HPV status." (PMID 36830672, 2023). "CAV1 and CAV2 regulate processes, including tumor growth, cell migration and metastasis, angiogenesis, and drug resistance." (PMID 36830672, 2023). "In this study, down-regulation of CAV2 and MME in EBC tumor tissues was associated with poor prognosis." (PMID 35132081, 2022). "CAV2 was found to upregulate the proteins levels of S100s, promoting invasion and migration and downregulating the expression of members as tumor suppressors." (PMID 36114176, 2022). "Recently, some studies believe that CAV1 and CAV2 were expressed low as tumor suppressors in primary BC and cell lines." (PMID 36147736, 2022). "Taken together, our findings suggest that both the high M1-like to M2-like TAM ratio and the increased numbers of infiltrating M1-like TAMs are required to initiate the anti-tumor immune response in Cav-2 KO mice." (PMID 31831780, 2019). "Co-injection of Cav-2 KO bone marrow cells transiently suppressed LLC tumor growth in WT mice compared to their respective control counterparts co-injected with WT bone marrow cells." (PMID 31831780, 2019). "Initially, LLC cells were s.c. implanted into the flanks of WT and Cav-2 KO mice and tumor growth was determined as described in experimental procedures." (PMID 31831780, 2019). "The slower tumor regression observed in Cav-2 KO mice s.c. implanted with LLC compared to CMT 167 proved to be critical for obtaining cell numbers sufficient for further analysis by flow cytometry as well as qRT-PCR and cytokine assays." (PMID 31831780, 2019). "Conversely, consistent with the angiostatic effects of CXCL9 and CXCL10 by binding to their receptor CXCR338, we earlier reported reduced angiogenesis in LLC tumors from Cav-2 KO mice as early as day 6 after tumor cell implantation." (PMID 31831780, 2019). "More specifically, we used flow cytometry to determine M1-like vs. M2-like TAM numbers from LLC tumors extracted at day 8, when the tumor volume was still comparable between mice co-injected with Cav-2 KO vs. WT bone marrow cells." (PMID 31831780, 2019). "Taken together, our results suggest that Cav-2 KO bone marrow-derived hematopoietic cells are able to directly suppress LLC tumor growth and that the increased numbers of M1-like TAMs are involved." (PMID 31831780, 2019). "Overall, our RT-qPCR and cytokine assay data suggest increased infiltration of M1-like TAMs into LLC tumors implanted into Cav-2 KO mice, which likely initiates T cell infiltration and consequently results in tumor regression." (PMID 31831780, 2019). "Next, we examined if changes in various TAM subsets is involved in initiating the tumor growth suppression by Cav-2 KO bone marrow cells." (PMID 31831780, 2019). "Transfer and co-injection of Cav-2 KO bone marrow (origin of TAMs) suppresses tumor growth and increases numbers of M1-polarized TAMs in wild type (WT) mice." (PMID 31831780, 2019). "Here, using our unique anti-tumor model involving Cav-2 deficient mice, we demonstrate that the combination of M1 phenotype and augmented TAM infiltration is likely required to initiate the LLC tumor eradication." (PMID 31831780, 2019).